IL6 (interleukin 6)
Diseases named in the same sentence as IL6 in open-access papers (continued):
Sharing a sentence is not in itself a finding about the gene and the disease.
chorioamnionitis (continued). "We compared the ability of suPAR to identify FIRS and FIRS with histological chorioamnionitis with that of other inflammatory biomarkers, such as MMP-8, TNF-α, and IL-6." (PMID 38200448, 2024). "Interleukin (IL-6), CRP, amniotic neutrophil elastase, blood, and vaginal flora serve as biomarkers of chorioamnionitis." (PMID 39574982, 2024). "In summary, our study established close similarities in IL6 signaling during chorioamnionitis/IUI between human subjects (both term and preterm deliveries) and a non-human primate (NHP) model, allowing understanding mechanism of IL6 regulation." (PMID 38895127, 2024). "In ROC analysis, suPAR showed similarly good characteristics in diagnosing FIRS with histological chorioamnionitis, whereas MMP-8, TNF-α and IL-6 performed better in identifying FIRS alone." (PMID 38200448, 2024). "Close monitoring for signs of chorioamnionitis (e.g., body temperature, CTG, CRP, leucocytes, IL-6, procalcitonin and amniotic fluid examinations) is necessary to minimize the risk of neonatal and maternal complications." (PMID 36143388, 2022). "The vaginally obtained amniotic fluid IL-6, MMP-8, and TNF-α seem to be good predictors for chorioamnionitis of patients with preterm premature rupture of membranes before 34 weeks of gestation." (PMID 33800521, 2021). "Vaginally obtained amniotic fluids with IL-6, MMP-8, and TNF-α seem to be good predictors for chorioamnionitis in patients with preterm premature rupture of the membranes before 34 weeks of gestation." (PMID 33800521, 2021). "An elevated level of cytokines IL-1β, IL-6, TNFα, IFNγ, EGF, MIP3α in patients with PROM and intra-amniotic infection." (PMID 34745106, 2021). "Our findings, as well as those presented in previous reports, support the use of IL-6, TNF-α, and MMP-8 analyses for the identification of chorioamnionitis in patients presenting with PPROM." (PMID 33800521, 2021). "Lastly, it is known that IL-6 and TNF-alpha are increased in chorioamnionitis and these cytokines also result in methylation at the Foxp3 promoter, that then down regulates Treg cell development." (PMID 30473713, 2018). "Elevated concentrations of IL-1β, IL-6, IL-8, and TNF-α are usually found within the amniotic fluid of patients with chorioamnionitis and/or funisitis." (PMID 22952869, 2012). "According to our findings, at a cord blood IL-6 threshold ≥ 11.92 pg/mL, in the FIRS group, we identified a sensitivity of 88.1% for chorioamnionitis and 89.2% for funisitis and a specificity of 45.8% for chorioamnionitis and 47.7% for funisitis." (PMID 41010644, 2025). "In contrast, the suPAR AUC was not significantly different from that of MMP-8 and IL-6 for identifying FIRS with histological chorioamnionitis." (PMID 38200448, 2024). "In this study the median suPAR concentration was significantly higher in the group FIRS (defined by high interleukin-6 level in the umbilical cord) with histological chorioamnionitis compared to the group neither FIRS nor HCA." (PMID 39227528, 2024). "Elevated concentrations of IL-6 were found in cord plasma in chorioamnionitis, while mononuclear cells from neonates expressed no IL-6 mRNA in vivo." (PMID 37685739, 2023). "Unexpectedly, we did not establish any EGF association with histological chorioamnionitis, FIRS, or inflammatory cytokines such as IL-6, TNF-α, and MMP-8." (PMID 35328399, 2022). "Despite structural similarities and shared roles in inflammation, leptin and IL-6 have contrasting effects on neurodevelopment, and the relative importance of maternal diabetes or chorioamnionitis on fetal hormone exposure has not been defined." (PMID 35197933, 2022). "The sensitivity, specificity, positive prognostic value (PPV), and negative prognostic value (NPV) of the IL-6 cut-off for chorioamnionitis were 88%, 70%, 67%, and 89%, respectively." (PMID 33800521, 2021).
chorioamnionitis (continued). "In this study, we found that women with chorioamnionitis had higher vaginal fluid IL-6 and TNF-α concentrations compared to women without this infection." (PMID 33800521, 2021). "Although interleukin-6 and -8 in amniotic fluid can indicate intra-amniotic infection, we did not evaluate them." (PMID 34987587, 2021). "The strength of this study is that this is one of the largest reported studies that has sought to determine the cut-off levels for IL-6 and TNF-α, and it is the first study to determine a cut-off level for MMP-8 in vaginally obtained amniotic fluid for the prediction of chorioamnionitis." (PMID 33800521, 2021). "To date, several studies have identified maternal blood biomarkers that are predictive of histological chorioamnionitis, including various host proteins secreted in response to microbial pathogens, such as serum CRP, MMP-9, IL-6, S100 calcium-binding proteins A8/A9 and IGFBP-1." (PMID 34046191, 2021). "Among the 232 women, 28 patients had positive AF cultures, 82 had an elevated AF IL-6 levels (≥ 1.0 ng/mL), 34 had elevated AF WBC counts (≥ 50 cells/mm3), and 56 had histologic chorioamnionitis, and several patients simultaneously met the criteria used in this study for defining IUI." (PMID 33184413, 2020). "The sixth sample with H1.5 level of 2.11 ng/mL belonged to the group with MIAC alone but the IL-6 level of this sample was more than 15,000 pg/mL despite the absence of chorioamnionitis or funisitis." (PMID 33077789, 2020). "Moreover, during chorioamnionitis, the fetus can develop a fetal inflammatory response syndrome (FIRS), which is characterized by increased systemic interleukin 6 (IL-6) and interleukin 8 (IL-8) levels." (PMID 32883198, 2020). "Similarly, IL-6 was found elevated only in the umbilical cord, especially in PPROM with microbial invasion and histologic chorioamnionitis." (PMID 28890425, 2017). "Preterm infants with funisitis were found to have elevated rates of chorioamnionitis and positive amniotic-fluid cultures, a lower gestational age at delivery, and higher cord blood IL-6 concentrations than those without funisitis." (PMID 25520716, 2014). "Conversely, severe protracted chorioamnionitis with cellular necrosis was the predominant lesion phenotype in BALB/c mice, which also exhibited a significant increase in placental expression of IL-1α, IL-1β, IL-6, TNF-α, S100A8, and S100A9 (P<0.01)." (PMID 22952869, 2012). "The median cord IL-6 level was 34.7 pg/mL with no histologic chorioamnionitis, 98.6 pg/mL with Grade 1 and 359.1 pg/mL with Grade 2 histologic chorioamnionitis (P<.001)." (PMID 22412842, 2012). "At delivery, maternal serum IL-6 levels, but not IL-8 levels, were significantly higher among those with histologic chorioamnionitis." (PMID 22412842, 2012). "Studies on biological markers of intrauterine and intra-amniotic infection such as FNF and interleukin-6, are consistent with histological and microbiological observations: it takes an average of 7 or 8 weeks for a preterm delivery, sepsis or fetal/neonatal death to occur, after a positive test." (PMID 20591191, 2010). "Compared to Negative Control Group animals, the 2 d Sterile Chorioamnionitis Group animals had significantly increased placental mRNA for IL6 (mean dCt difference = 2.77; 95% CI 5.01 to 0.0.53, p = 0.015) and IL18 (mean dCt difference = 1.79; 95% CI 3.28 to 0.29, p = 0.019)." (PMID 40464837, 2025). "Thus, in our chorioamnionitis model, A20 may regulate TLR-induced airway inflammation accompanied by a reduction of IL-1β, IL-6, IL-8, and TNF-α." (PMID 35096271, 2022). "In a study of lipid mediators in amniotic fluid, samples from patients with clinical chorioamnionitis had higher levels of IL-6 and lower levels of inflammation resolving mediators derived from omega-3 fatty acids compared to patients without clinical chorioamnionitis." (PMID 32635612, 2020).
chorioamnionitis (continued). "Regarding the prediction of intra-amniotic infection, the following variables were entered into the multivariate logistic regression analysis as significant predictors in the univariate analyses (P < 0.1): gestational age at sampling, serum CRP and plasma IL-6 levels, and cervical length." (PMID 29743041, 2018). "Targeted analysis of IL1 A, IL1B, IL6, and CD14 in maternal plasma of the 2 d Sterile Chorioamnionitis Group animals did not improve predictive values with a mean AUC of 0.46 (95% CI 0.13–0.79), Sensitivity 67%, Specificity 57%, PPV 0.67, NPV 0.57." (PMID 40464837, 2025). "In our study, differences in IL-1β, IL-6 and IL-8 expression did not correlate with ureaplasma CFU/mL or gram of tissue, or the severity of histological chorioamnionitis." (PMID 22253806, 2012). "However, corresponding elevated maternal plasma markers of inflammation (IL-1β, IL-2, IL-6, IFN-γ and TNF-α) have not been shown to be accurate for the diagnosis of chorioamnionitis." (PMID 40464837, 2025). "However, all the samples were obtained using the same technique, and the values of IL-6, TNF-α, and MMP-8 were statistically higher in the chorioamnionitis group than in the noninfection group." (PMID 33800521, 2021). "Intra-amniotic injections in fetal sheep of IL-1 or E. coli endotoxin lipopolysaccharides (LPS), but not IL-6, IL-8, or TNF-α, induce chorioamnionitis and early lung maturation as measured by large increases in pressure–volume curves and lung mechanics and gas exchange within 5 to 7d." (PMID 26301222, 2015).
type 1 diabetes (124 papers, 2006 to 2026). "Type 1 diabetes is characterized by elevated levels of pro-inflammatory cytokines, such as IL-6, TNF-α, and IL-1β, typically transient and linked to the acute immune response against the virus." (PMID 39861189, 2025). "Consistent with our finding of the protective effect of IL-2 signalling, we found that IL-6 signalling increased the risk of type 1 diabetes." (PMID 39271518, 2024). "Soluble glycoprotein 130 inhibits IL-6 trans-signalling, whereas enhanced T cell responses to IL-6 in type 1 diabetes were shown to be associated with early clinical disease." (PMID 36907892, 2023). "Blimp-1 and IRF4 can be activated by factors other than B cell receptor signalling, such as IL-21 and IL-6 or IFNα and IL-6, cytokines implicated in the pathogenesis of type 1 diabetes." (PMID 36508037, 2023). "In cases, SFAs were associated with several immunological markers (CXCL10, IL-6, IL-9, IL-17, and CM-CSF) previously linked to the type 1 diabetes disease process." (PMID 35693790, 2022). "We observed that in case children, several SFAs and CLA were associated with many immunological markers [CXCL10 (IP-10), IL-6, IL-9, IL-17, and CM-CSF] that have been linked to the development of type 1 diabetes." (PMID 35693790, 2022). "The present study provides a quantitative analysis regarding the Th17/Treg cell balance in peripheral blood of children with type 1 diabetes and its association with serum IL-6 level." (PMID 23533301, 2013). "Our current work shows the association between IL-6 serum level and Treg/Th17 subsets in type 1 diabetes patients." (PMID 23533301, 2013). "In IL-6 polymorphisms, females with the CC genotype of IL-6 -174 G/C have an earlier onset of type 1 diabetes when compared with IL-6 -174G allele females and all males." (PMID 21835044, 2011). "Although TAF5L (C744A; rs3753886), PDCD1 (7146G>A; rs11568821), TCF7 (C883A; rs5742913) and IL6 (IL6-174G>C; rs1800795) have previously been associated with type 1 diabetes, the possibility remains that these associations are false positives." (PMID 18045485, 2007). "As IL6 has been reported to be associated with type 1 diabetes, we sought to replicate this association by genotyping IL6-174G>C (rs1800795) and a set of tag SNPs for the IL6 region." (PMID 18045485, 2007). "To test for an association between type 1 diabetes and the IL6 region, we adopted a LD mapping approach." (PMID 18045485, 2007). "However, the results obtained in genetic studies seeking to associate IL-6 with type 1 diabetes are inconsistent." (PMID 33920401, 2021). "Recent studies suggest an association between IL-6 and the development of type 1 diabetes." (PMID 31772933, 2019). "Consequently, additional studies will be required to ascertain the contribution of TAF5L, PDCD1, TCF7 and IL6 to type 1 diabetes susceptibility." (PMID 18045485, 2007). "Type 1 diabetes caused a significant increase in the mean fold change in the relative mRNA expression of the renal proinflammatory markers such as nuclear factor-κB NFKβ, tumor necrosis factor (TNFα), interleukin-1β (IL-1β), and interleukin-6 (IL-6) compared with the control group." (PMID 38044936, 2023). "Using co-localisation and Mendelian randomisation, we found genetic evidence to support the role of IL-2 and IL-6 signalling in the pathogenesis of type 1 diabetes." (PMID 39271518, 2024). "For example, Cxcl12 supports β cell survival in a mouse model of type 1 diabetes and recruits macrophages to promote β cell regeneration after damage, while IL-6 has been shown to directly enhance insulin secretion." (PMID 38885342, 2024). "In conclusion, our results provide genetic evidence that IL-2, IL-6 and TYK2 signalling are associated with type 1 diabetes risk." (PMID 39271518, 2024). "TCR signals plus IL6-induced pSTAT1 and pSTAT3 regulate early differentiation of Tfh cells, implicated in SLE and Type 1 diabetes (T1D)." (PMID 37275873, 2023).
type 1 diabetes (continued). "In type 1 diabetes, levels of IL-6 (p = 0.030) and TNF-α (p = 0.019) were increased in males compared to females." (PMID 37189645, 2023). "In turn, in case children at the age of 6 months, n-6 LA and AA were directly associated with cytokines (IL-6, IL-9, and CXCL10), which have been previously linked to pre-clinical and clinical type 1 diabetes." (PMID 35693790, 2022). "We performed short-term interventions in individuals with type 1 diabetes using anti–IL-6 (siltuximab) or anti–IL-6 receptor (IL-6R; tocilizumab) therapies and investigated the impact of this in vivo blockade on T cell fate and function." (PMID 36282595, 2022). "In this study, we demonstrate that a butyric acid-producing Leuconostoc mesenteroides (L. mesenteroides) EH-1 strain isolated from Mongolian curd cheese can reduce blood glucose and IL-6 in the type 1 diabetic mouse model." (PMID 32404878, 2020). "High IL-6 level was identified in early stage of type 1 diabetes proposing IL-6 is involved in islet cells impairment." (PMID 28484449, 2017). "Our results also add to the large body of literature that indicates a role for immune activation and proinflammatory cytokines, such as TNF-α, IL-1 and IL-6, in the promotion of beta cell death in type 1 diabetes." (PMID 24264051, 2014). "Among various cytokines involved in promoting and maintaining chronic inflammatory response, TNF-α (tumor necrosis factor-α) and IL-6 are systemically increased in patients with type 1 diabetes." (PMID 24523574, 2014). "IL-6 levels increased throughout the day peaking at 16:00 in both the patients with type 1 diabetes (median increase from fasting: 610% increase) and the controls (570% increase)." (PMID 24959195, 2014). "Some groups reported lower levels of serum IL-6 in type 1 diabetes while others have found normal or even increased levels of IL-6." (PMID 24278195, 2013). "We found some evidence of associations between type 1 diabetes and TAF5L, PDCD1, TCF7 and IL6 (ORs = 1.05 – 1.13; P = 0.0291 – 4.16 × 10-4)." (PMID 18045485, 2007). "Thus, natural history studies and clinical prevention trials should pinpoint the optimal stage of pathogenesis at which to interfere with IL-2, IL-6 or TYK2 signalling to prevent type 1 diabetes." (PMID 39271518, 2024). "To address this gap in knowledge, we used samples from 2 independent mechanistic clinical studies in patients with established type 1 diabetes (T1D) to compare the effect of anti–IL-6 (siltuximab) and anti–IL-6R (tocilizumab) therapies on T cell fate and function." (PMID 36282595, 2022). "IL-6 signaling and type I diabetes mellitus signaling were enriched in splenic Treg (E-MTAB-7961)." (PMID 34084175, 2021). "A study conducted in Poland in a group of 71 children (aged 7–17) with type 1 diabetes demonstrated that from the first years of the disease, elevated concentrations of inflammation markers (hsCRP, IL-6, IL-1) could be observed compared to healthy children." (PMID 34836227, 2021). "Type 1 diabetes is characterized by the presence of hyperglycemia together with insulin resistance, oxidative stress as well as elevated production of cytokines, such as C-reactive protein, interleukin (IL)-6 and tumor necrosis factor (TNF)-α7." (PMID 32404878, 2020). "Interestingly, our EC model showed an increase in CXCL10, ICAM1, IL-6, and MIF, which are associated with type I diabetes development." (PMID 31835296, 2019). "The first one was a study including also type 1 diabetes patients; it was determined in this study that serum IL-6 levels were effective in ulcer classification according to Texas classification but it was not an independent variable for the determination of infection severity." (PMID 29675434, 2018). "In addition, CV-B4 infections, which are mainly associated with meningoencephalitis, neonatal myocarditis and type-1 diabetes, can also promote cytokine and chemokine production in host cells (e.g., IL-6, LIF, and GM-CSF)." (PMID 30545363, 2018).